AXL (AXL receptor tyrosine kinase)
Diseases named in the same sentence as AXL in open-access papers (continued):
Sharing a sentence is not in itself a finding about the gene and the disease.
breast tumor (11 papers, 2011 to 2022). "AXL has also been implicated in more rare forms of breast tumors, including in phyllodes tumors of the breast, which are tumors that originate in stromal tissue, as well as in male breast cancer." (PMID 32148495, 2020). "A recent study investigated the expression of AXL, a receptor tyrosine kinase, in breast tumors and cell lines, and the viability of an AXL-targeted CAR-T cell treatment." (PMID 34729098, 2021). "In this review, we will illustrate the biological role played by AXL in breast tumor cells, highlighting its molecular and biological features, its involvement in tumor progression and its implication as a target in ongoing clinical trials." (PMID 33182542, 2020). "The use of murine models of HER2-positive breast tumors has shown, in a recent study, that the interaction between the two receptors stabilizes and activates AXL in membrane, favoring intravasation and extravasation phenomena." (PMID 33182542, 2020). "Reverse-phase protein array analysis in breast tumors revealed evidence of cross-talk between AXL and the RTK MET, along with potential physical interaction between these two receptors." (PMID 32148495, 2020). "The microenvironment components that were functionally predicted to induce AXL expression on MEMA, were found co-expressed by cells in breast tumor microenvironments adjacent to cells expressing AXL." (PMID 29719832, 2018). "In sum, future work should seek to further uncover AXL's role in the breast tumor so that combination therapies could be developed that co-target AXL along with other intracellular players." (PMID 32148495, 2020). "We showed this functionally on MEMA, in follow up validation cell culture experiments, and using RNA in situ hybridization and immunohistochemistry, we demonstrated coordinated expression of these microenvironment factors with AXL expressing cells in breast tumors." (PMID 29719832, 2018). "AXL overexpression has been linked to Imatinib-resistance in gastrointestinal stromal tumors, Nilotinib-resistance in CML and Lapatinib-resistance in HER-2 positive breast tumor cells." (PMID 25193853, 2014). "Intriguingly, two AXL-negative relapsed breast tumors displayed minimal upregulation of PS-RIP gene expression when compared to a non-relapsed sample that has a low basal AXL expression." (PMID 33850249, 2021). "In HER2-positive breast tumors, TGF-β/AXL axis play an important role in tumor progression." (PMID 33182542, 2020). "To further determine whether AXL is involved in E1A-mediated EGFR-TKI sensitization in vivo, we performed an orthotopic breast tumor growth assay in an animal model." (PMID 27590506, 2016). "To ask whether metastatic cancer relapse associated with therapy is linked with decreased PS-RIP, we further inspected both non-relapsed and relapsed breast tumor tissues that stained positive to high AXL and correlated their expression with patient’s HER2 status." (PMID 33850249, 2021).
esophageal cancer (11 papers, 2016 to 2025). A primary or metastatic malignant neoplasm involving the esophagus. "C-ABL and p73 play important roles in the process of cellular apoptosis caused by DNA damage, and both are interfered with by AXL to enhance cisplatin resistance in esophageal cancer through impeding nuclear aggregation of c-ABL and impairing p73 protein stability." (PMID 37328828, 2023). "Blocking JNK (c-Jun N-terminal kinase)/AP-1 inhibits AXL transcription and attenuates drug resistance to PI3Kα therapy in esophagus cancer and head and neck squamous cell carcinoma." (PMID 37328828, 2023). "In particular, bemcentinib, a highly selective small molecule AXL inhibitor, was shown to block tumor growth in AXL‐expressing metastatic breast and esophageal cancer models." (PMID 34877810, 2021). "The AP1 transcription factors c-JUN and c-FOS can mediate AXL overexpression in head and neck and esophageal cancers." (PMID 32148495, 2020). "The results and references in the present study confirm that GAS6/AXL is an important pathway affecting the invasion and metastasis of esophageal cancer." (PMID 31110076, 2019). "The present study demonstrates that QGS inhibits invasion and migration of ESCC cells by regulating the Gas6/AXL signaling pathway and thereby causing a decrease in PI3K/AKT and NF-κB signaling, preventing metastasis of esophageal cancer." (PMID 31110076, 2019). "A growing body of studies has demonstrated the promise of AXL as a novel target for cancer targeted therapy, including in esophageal cancer." (PMID 27172793, 2016). "Overexpression of AXL promotes cisplatin resistance through regulation of c-ABL expression in esophageal cancer." (PMID 27590506, 2016). "AXL has been frequently linked to EMT in some cancers, including esophageal cancer." (PMID 31781483, 2019). "On the other hand, inhibition of GAS6/AXL axis reduces Snail and N-cadherin but upregulates E-cadherin, inhibiting EMT in esophageal cancer cells." (PMID 37328828, 2023).
bladder cancer (10 papers, 2015 to 2025). "Because GAS6 has the capacity to stimulate AXL-mediated chemotaxis, malignant bladder cancer cells can utilize GAS6-AXL signaling to recruit PD1hi CD200hi CD4+ exhausted T cells and indirectly promote EMT." (PMID 38137547, 2023). "Next, potential integrated prognosis-related proteins (IPRPs) model (including BECLIN, PKCALPHA, EGFR, ANNEXIN1, AXL and SRC) was constructed to assess the survival risk score of bladder cancer." (PMID 33830879, 2021). "It has been proposed that FOSL1 control the motility of bladder cancer cells via transcriptional up-regulation of the receptor tyrosine kinase AXL, which is also involved in squamous cell carcinoma growth through c-Jun activation." (PMID 31438567, 2019). "Loss-of-function experiments identified a TYRO3-dependency of bladder carcinoma-derived cells both in vitro and in a mouse xenograft model, whereas AXL and MERTK depletion had only a minor impact on cell viability." (PMID 30765874, 2019). "Similar findings have been described in bladder cancer where AXL mRNA is induced after MET activation and downstream MEK/ERK signaling." (PMID 28251492, 2017). "In bladder cancer T24 cells, AXL was significantly downregulated by JorA." (PMID 37587470, 2023). "AXL mRNA expression in bladder cancer (NMIBC and MIBC) patients and normal controls." (PMID 26225770, 2015). "Binding sites for the FOS and JUN components of AP1 are present in the AXL promoter and functional studies have confirmed their involvement in the regulation of AXL expression in chronic myeloid leukemia (CML) and bladder cancer, respectively." (PMID 28251492, 2017). "Oncogenic dependency on members of the TAM tyrosine kinase receptor family (TYRO3, AXL, MERTK) has been reported in several cancer types, but their role in bladder cancer has never been explored." (PMID 30765874, 2019). "The TAM family of receptor tyrosine kinases (RTKs), which includes TYRO3, AXL and MERTK, has emerged as new therapeutic target in many types of cancer, but their role in bladder cancer has not yet been determined." (PMID 30765874, 2019).
chronic lymphocytic leukemia (10 papers, 2014 to 2023). "In preclinical studies, TP-0903 — a small molecule originally developed as an AXL inhibitor — demonstrated anticancer activity in chronic lymphocytic leukemia (CLL), invasive breast cancer, and neuroblastoma." (PMID 33268594, 2020). "Furthermore, miR-34a was also shown to target AXL, a receptor tyrosine kinase that activates PI3K/AKT signaling, and to be overexpressed in chronic lymphocytic leukemia (CLL)." (PMID 34944752, 2021).
endometrial cancer (10 papers, 2016 to 2025). Primary or metastatic malignant neoplasm involving the endometrium (mucous membrane that lines the endometrial cavity). "To determine whether PI3K/AKT signaling is affected by loss of AXL in endometrial cancer cells, we performed Western blot analyses evaluating levels of AKT phosphorylated at Ser473 (P-AKT) on shSCRM and shAXL ARK1 and Hec50a cells." (PMID 27764792, 2016). "In endometrial cancer cells, inhibition of AXL down-regulates various glycolytic metabolites, leading to increased sensitivity to paclitaxel." (PMID 37328828, 2023). "Although, there are fewer studies on AXL in the uterus, a recent study reported that AXL is highly detected in endometrial cancer." (PMID 36077170, 2022). "Studies have shown that AXL gene silencing inhibited the migration and invasion of endometrial cancer cells." (PMID 33033380, 2020). "To examine the role of AXL in proliferation of EC cells, we used short hairpin RNAs (shRNAs) to generate AXL-deficient metastatic endometrial cancer cell lines (ARK 1 and Hec50a) and confirmed AXL knockdown by Western analyses." (PMID 27764792, 2016). "Pharmacological inhibition using R428 was also used to inhibit endometrial cancer cell invasion in vitro, suggesting clinical relevance of AXL inhibition." (PMID 27764792, 2016). "Western blot analysis showed that exogenous GAS6 induced phosphorylation of AXL in both endometrial cancer cell lines." (PMID 27764792, 2016). "Together, these findings underscore the therapeutic potentials of AXL as a candidate target for treatment of metastatic endometrial cancer." (PMID 27764792, 2016). "Overall, these findings demonstrate that knockdown of AXL expression in ARK 1 cells inhibited endometrial cancer metastasis." (PMID 27764792, 2016). "AXL is overexpressed or ectopically expressed in multiple cancers including breast, prostate, ovarian, and endometrial cancer." (PMID 27764792, 2016). "To define the role of AXL in endometrial cancer, we first screened five EC cell lines for AXL expression." (PMID 27764792, 2016). "Advanced-stage and high-grade endometrial carcinomas also expressed more AXL than early-stage and low-grade carcinomas." (PMID 27764792, 2016). "Since AXL inhibitors are kinase inhibitors and PMSCs are a proliferative cell population with uterine characteristics, we examined a multikinase inhibitor, lenvatinib, which is effective against endometrial carcinoma." (PMID 38598342, 2024). "These lncRNA-mRNA-miRNA regulatory associations have been observed in many diseases, including endometrial cancer; lncRNA H19, for example, was reported to accelerate tumor formation in endometrial cancer by regulating HIF-1α/AXL signaling through competition for miR-20b-5p." (PMID 33584822, 2021). "Our data show that whereas 24% (15/63) of normal specimens expressed high levels of AXL (score 2, or 3), 63% (180/287) of primary type I and type II endometrial carcinoma samples and 86% (286/332) of endometrial cancer in all stages (primary tumors and metastases) expressed AXL (P<0.0001 for both)." (PMID 27764792, 2016). "Taken together, our data suggest that AXL may be a novel therapeutic target to inhibit endometrial cancer metastasis." (PMID 27764792, 2016). "Thus, we conclude that AXL is not necessary for endometrial cancer cell proliferation in vitro." (PMID 27764792, 2016).
small cell lung carcinoma (10 papers, 2016 to 2024). Small cell lung cancer (SCLC) is a highly aggressive malignant neoplasm, accounting for 10-15% of lung cancer cases, characterized byrapid growth, and early metastasis. "Of interest, we found that the γ-secretase–uncleavable AXL mutant caused an elevated chemoresistance in non–small-cell lung cancer cells." (PMID 28034848, 2017). "Earlier research has demonstrated that in small-cell lung cancer, the activation of Chk1 through the upregulation of AXL and MET pathways is a significant mechanism of resistance to AZD-1775." (PMID 37296592, 2023). "Indeed, AZD1775-resistant small cell lung cancer models were shown to have elevated expression of AXL, pS6, and MET genes that a WEE1/AXL or WEE1/mTOR inhibitor combination could overcome the resistance in vitro and in vivo." (PMID 30068368, 2018). "Recently, increased expression and activation of AXL was demonstrated to mediate primary and acquired resistance to AZD1775 in small-cell lung cancer." (PMID 32195191, 2020). "A previous study has shown that upregulation of receptor tyrosine kinase AXL or downstream targets of AXL and PI3K/mTOR pathways were the strongest markers of resistance to Adavosertib identified in the proteome of a resistant small cell lung carcinoma (SCLC) cell line." (PMID 38020882, 2023). "Further, not all NSCLC erlotinib-resistance mechanisms reported in the literature were exhibited by the PERCs; we found no compelling evidence of transformation to small cell lung cancer, epithelial-to-mesenchymal transition or activation of IGF1R, AXL or NFK-B." (PMID 26891683, 2016).
oral squamous cell carcinoma (9 papers, 2015 to 2025). "Fibroblasts transfer miR-34a-5p in exosomes to oral squamous cell carcinoma, suppressing their proliferation and metastasis by binding and suppressing AXL-mediated signaling." (PMID 37046676, 2023). "Fibroblasts transfer miR-34a-5p in exosomes to oral squamous cell carcinoma cells and inhibit their proliferation and metastasis by binding and suppressing AXL-mediated signaling." (PMID 37046676, 2023). "have demonstrated that exosomal miR-34a-5p was transferred from fibroblasts to oral squamous cell carcinoma cells and can bind to its direct downstream target AXL to suppress oral squamous cell carcinoma cell proliferation." (PMID 35058933, 2021). "In oral squamous cell carcinoma (OSCC) is further increased by the miR-34a-5p/AXL axis." (PMID 39187523, 2024).
thyroid cancer (9 papers, 2007 to 2025). "In the PROS pathway, the PROS1 ligand and its receptor AXL are overexpressed in thyroid cancer, while AXL blockade suppresses the invasion of thyroid cancer cells." (PMID 37874419, 2023). "Recent studies have also shown that the intensity of positive AXL staining in the cancer tissues of PTC patients is positively correlated with radioactive iodine-refractory thyroid cancer, disease recurrence, and poor prognosis." (PMID 36203174, 2022). "GAS6 was secreted only by thyroid cancer cells (NIM) that were used as a positive control, suggesting a ligand-independent activation of AXL in human CRC cells." (PMID 25966280, 2015). "AXL and its ligand GAS6 mRNA were also screened by real time-PCR (RT-PCR) using TPC1 and CAL62, two thyroid cancer cell lines, as positive controls." (PMID 25966280, 2015). "According to a previous report, TYRO3 and AXL were not expressed in normal thyroid cells, but showed remarkably increased expression in thyroid cancer cells, thereby contributing to the resistance of thyroid cancer to existing targeted treatments." (PMID 34721022, 2021).
mesothelioma (8 papers, 2012 to 2025). A usually malignant and aggressive neoplasm of the mesothelium which is often associated with exposure to asbestos. "Dysregulation and activation of Gas6/AXL tyrosine kinase signaling are associated with mesothelioma progression, but the mechanisms of these AXL tumorigenic roles are poorly understood." (PMID 32992696, 2020). "Previous studies have shown that AXL is a crucial protein that is activated in mesothelioma to cause growth and invasiveness." (PMID 32992696, 2020). "Further, high AXL expression in mesothelioma is significantly associated with poorer survival." (PMID 32992696, 2020). "The current cell component separation showed that the full-length AXL can also translocate into the nucleus in mesothelioma." (PMID 32992696, 2020). "Herein, we firstly analyzed AXL expression between mesothelioma and other tumor types by using the published TCGA expression profiling data on mesothelioma." (PMID 32992696, 2020). "AXL expression was stronger in mesothelioma than most of the other tumor types from the TCGA gene expression profile dataset." (PMID 32992696, 2020). "A better understanding of mesothelioma biology—including GAS6/AXL signaling pathways —will likely be crucial in identifying biologically rational targets for novel therapies." (PMID 32992696, 2020). "Our previous studies indicate that activation of Gas6/AXL signaling plays essential functional roles in mesothelioma tumorigenesis." (PMID 32992696, 2020). "Histologic subtype analyses further showed that higher AXL expression correlated with poorer overall survival in biphasic (p = 0.0023) and epithelioid (p = 0.0032) mesotheliomas." (PMID 32992696, 2020). "We also show that AXL inhibition by a selective drug inhibits mesothelioma cell viability, migration, and invasion." (PMID 32992696, 2020). "The current results and our previous studies show that AXL expression is stronger in mesothelioma, particularly those with spindle-cell components, than in most other cancer types." (PMID 32992696, 2020).